NDP (norrin cystine knot growth factor NDP)
Description:
Activates the canonical Wnt signaling pathway through FZD4 and LRP5 coreceptor. Plays a central role in retinal vascularization by acting as a ligand for FZD4 that signals via stabilizing beta-catenin (CTNNB1) and activating LEF/TCF-mediated transcriptional programs. Acts in concert with TSPAN12 to activate FZD4 independently of the Wnt-dependent activation of FZD4, suggesting the existence of a Wnt-independent signaling that also promote accumulation the beta-catenin (CTNNB1). May be involved in a pathway that regulates neural cell differentiation and proliferation. Possible role in neuroectodermal cell-cell interaction.
Synonyms: EVR2; norrin; FEVR; ND
Tractability: Small molecule: a structure with a bound ligand is known. Antibody: UniProt places it where antibodies can reach, with high confidence; UniProt predicts a signal peptide or a membrane-spanning region; its Gene Ontology location is reachable by antibodies, with medium confidence.
Gene: Protein-coding gene on chromosome X (43,948,772 to 43,973,395, reverse strand). Ensembl gene ENSG00000124479.
Subcellular location: Secreted
Subcellular location (Human Protein Atlas): Vesicles; Nucleoli; Nucleoplasm; Predicted to be secreted
Gene Ontology:
Molecular function: cytokine activity; frizzled binding; protein binding; protein homodimerization activity
Biological process: Norrin signaling pathway; positive regulation of DNA-templated transcription; positive regulation of transcription by RNA polymerase II; nervous system development; vacuole organization; visual perception; decidualization; extracellular matrix-cell signaling; Wnt signaling pathway
Cellular component: cell surface; extracellular region
Gene-disease validity (ClinGen):
ClinGen rates the evidence that NDP causes each of these diseases.
Norrie disease (X-linked): Definitive. A rare X-linked genetic vitreoretinal condition characterized by abnormal retinal development with congenital blindness.
Homologues: Orthologues: macaque NDP (100% identical), chimpanzee NDP (99% identical), guinea pig NDP (96% identical), pig NDP (96% identical), rabbit NDP (96% identical), mouse Ndp (94% identical), rat Ndp (94% identical).
Diseases named in the same sentence as NDP in open-access papers:
NDP is named in the same sentence as 93 diseases in open-access papers, as found by Europe PMC text mining. Sharing a sentence is not in itself a finding about the gene and the disease. The quoted sentences say what the papers report.
Norrie disease (48 papers, 2006 to 2026). "The essential role of Norrin to human retinal vasculature development was revealed by NDP gene variants that result in Norrie Disease or FEVR (Familial Exudative Vitreoretinopathy)." (PMID 41373499, 2025). "The genes mutated in these diseases include NDP (norrin) in Norrie disease and FZD4, LRP5, and TSPAN12 in FEVR." (PMID 41086024, 2025). "The pathogenic variants in the NDP gene lead to Norrie disease, a genetic disorder primarily manifesting as abnormal retinal development and severe vision impairment beginning from birth or early infancy." (PMID 41357583, 2025). "Norrie disease is a form of deaf blindness caused by mutations in NDP (Norrin Cystine Knot Growth Factor NDP gene)." (PMID 39585982, 2024). "Variants in NDP cause Norrie disease, an X-linked recessive dual-sensory disorder, or a milder ocular condition, familial exudative vitreoretinopathy (FEVR)." (PMID 39585982, 2024). "Variants in the gene NDP cause Norrie disease, a severe dual-sensory disorder characterized by congenital blindness due to disrupted retinal vascular development and progressive hearing loss accompanied by sensory hair cell death." (PMID 39585982, 2024). "Pathologic variants in NDP have been associated with several vascular retinopathies, including Norrie disease, FEVR, persistent fetal vasculature syndrome (PFVS), retinopathy of prematurity (ROP), and Coats disease." (PMID 37947657, 2023). "Our findings identified a novel missense mutation in the NDP gene associated with Norrie disease in China, expanding the mutation spectrum associated with ND." (PMID 38146894, 2023). "In conclusion, we have described a novel mutation in the NDP gene in a Chinese family with Norrie disease." (PMID 38146894, 2023). "Taken together, the clinical findings were suggestive of Norrie disease or X-linked familial exudative retinopathy, secondary to a damaging variant in NDP." (PMID 36084042, 2023). "Single nucleotide variants of the NDP gene cause Norrie disease, a rare X-linked disorder characterized by bilateral congenital blindness." (PMID 37628571, 2023). "While associated with Norrie disease, missense variants in NDP are also associated with diagnosed FEVR, both X-linked and sporadic." (PMID 37947657, 2023). "Norrie disease is caused by mutation of the NDP gene, presenting as congenital blindness followed by later onset of hearing loss." (PMID 35132964, 2022). "NDP mutations result in Norrie disease, an X-linked genetic disorder characterized by hypovascularization of the retina, retinal detachment, and severe visual impairments or loss of vision." (PMID 36432666, 2022). "Since Berger first reported NDP as the causative gene in Norrie Disease, many variants in NDP have been reported over the past 3 decades in patients diagnosed with both ND and FEVR as well as Coats disease and retinopathy of prematurity (ROP)." (PMID 35651932, 2022). "According to the original authors’ diagnoses, NDP variants were associated with Norrie Disease (140 variants), FEVR (62 variants), ROP (16 variants), Coats disease (3 variants) and bilateral Persistent Foetal Vasculature Syndrome (1 variant)." (PMID 35651932, 2022). "Norrie disease is an X-linked disorder caused by mutations in the Norrie disease pseudoglioma (NDP) gene." (PMID 35132964, 2022). "This study aims to analyze the Norrie disease gene (NDP) variants in patients with familial exudative vitreoretinopathy (FEVR) and their clinical features." (PMID 33588793, 2021). "NDP variants are already known to cause X-linked RD, along with other abnormalities, in human Norrie disease." (PMID 33945575, 2021). "Two families (32 and 55) diagnosed with Norrie disease carried two known NDP mutations, c.343C > T (p.R115X) and c.268C > T (p.R90C)." (PMID 33781268, 2021). "Most patients with NDP gene mutations show the Norrie disease phenotype; only 5% of patients show FEVR." (PMID 33588793, 2021).
Norrie disease (continued). "Recently, a human family has been described with Norrie disease caused by a microdeletion on the X chromosome that caused loss of norrin (NDP) but also deleted the genes encoding MAOA and MAOB." (PMID 34068984, 2021). "The analysis lasted 42 days and revealed a novel hemizygous substitution, NM_000266.3(NDP):c.385G > T, p.(Glu129*), in the NDP gene, which was associated with Norrie disease (OMIM #310600) inherited in X-linked recessive mode." (PMID 33092543, 2020). "Mutations in the NDP gene result in Norrie disease, which is primarily an eye disease that leads to blindness." (PMID 29860944, 2018). "Norrie disease is caused by mutations affecting the NDP (Norrie disease pseudoglioma) gene that is encoding for the Norrie protein and characterized by progressive deafness, mental retardation, but also congenital blindness due to malformations in the retina." (PMID 28575130, 2017). "Genetic testing revealed the p.(Arg121Gln) variant in the NDP gene, already associated in literature with Norrie disease (MIM ∗310600)." (PMID 28758032, 2017). "For example, mutation in NDP causes either FEVR or Norrie disease (a more severe phenotype), and mutation in LRP5 causes FEVR or osteoporosis pseudoglioma syndrome, a more severe phenotype." (PMID 23441120, 2013). "Mutations in the NDP gene encoding Norrin result in Norrie disease, an X-linked congenital syndrome characterized by retinal vascularization failure leading to blindness, often accompanied by microcephaly, deafness, hypogonadism, or mental retardation." (PMID 23840940, 2013). "Pathogenic variants in the NDP gene may lead to either a severe retinal phenotype associated with hearing loss (Norrie Disease, OMIM 310600) or a moderate retinal phenotype (Exudative Vitreoretinopathy, OMIM 305390)." (PMID 41174744, 2025). "However, it was of utmost interest that the Norrie disease-causing gene NDP showed the strongest downregulation in mutant reporter cells." (PMID 38994994, 2024). "A novel pathogenic NDP variant was identified in a patient with Norrie’s disease." (PMID 39495751, 2024). "Delivery of NDP gene therapy after the onset of the degenerative inner ear disease also ameliorated the cochlear pathology, supporting the feasibility of a clinical treatment for progressive hearing loss in people with Norrie disease." (PMID 37642150, 2023). "Norrie disease is associated with loss-of-function mutations in Norrin (NDP) (>100 mutations reported) whereas FEVR is caused by mutations in multiple genes including NDP/FZD4/LRP5/TSPAN12/ZNF408 and recently reported CTNNA1 and KIF11." (PMID 37887287, 2023). "Norrie disease is a recessive X‐linked disorder, caused by NDP gene mutation." (PMID 37642150, 2023). "Pathogenic variants in NDP (Xp11.3) may result in either a severe retinal phenotype associated with hearing loss (Norrie Disease) or a moderate retinal phenotype (Familial Exudative Vitreoretinopathy, FEVR)." (PMID 35651932, 2022). "However, individuals with X-linked FEVR, autosomal dominant FEVR, retinopathy of prematurity, and Norrie disease have also been reported to have mutations in NDP and FZD4 genes." (PMID 34485332, 2021). "The congenital retinal detachments in the form of fibrovascular retrolental masses and extensive vitreal haemorrhage, is more similar to that described in clinical cases of human Norrie disease than the other inherited retinopathies associated with NDP variants." (PMID 33945575, 2021). "NDP-related retinal diseases, caused by abnormalities in the NDP gene, include various progressive diseases with retinal vascular hypoplasia, such as Norrie disease, Coat’s disease, FEVR, persistent hyperplastic primary vitreous, and retinopathy of prematurity." (PMID 33588793, 2021). "NDP mutations can lead to familial exudative vitreoretinopathy (FEVR) or Norrie disease." (PMID 33781268, 2021).
Norrie disease (continued). "Another similarity between patients with mutations in the NDP gene and the mouse model of Norrie disease is that the retinal changes in Ndphy/- mice are accompanied by prominent defects within the retinal vasculature and by persistent hyaloid vessels in the vitreous." (PMID 28575130, 2017). "There are two parallel hypotheses relating to the disease mechanism of intellectual disability in Norrie Disease when caused by a large deletion: The first is that large deletions of the NDP gene are often accompanied by deletions of the monoamine oxidase (MAO) genes." (PMID 35651932, 2022). "ND is caused by the Norrie Disease Protein gene (NDP), which codes for norrin, a cysteine-rich protein involved in ocular vascular development." (PMID 21179243, 2010). "The cystine-knot protein Norrin (NDP), originally identified as the Norrie disease protein, is a secreted factor that reportedly promotes vascular growth in the retina and exhibits neuroprotective activity." (PMID 41357583, 2025). "Given that Fz4-mutant mice also display dilated vessels in the stria vascularis, it seems likely that WNT signaling via the NDP/FZ4/LRP5/TSPAN12 pathway also accounts for the stria vascularis vessel abnormalities in Norrie disease." (PMID 35132964, 2022). "Retinoschisis and Norrie disease are X-linked recessive retinal disorders caused by mutations in RS1 and NDP genes respectively." (PMID 34039417, 2021). "Previous studies have shown that most of the NDP gene mutations leading to the FEVR phenotype are missense mutations, while the nonsense, splice-site, and large deletion mutations mainly lead to Norrie disease." (PMID 33588793, 2021). "A key component of this evidence is NDP's role in eye development and the Mendelian diseases Norrie disease and FEVR248; clinical features of these diseases include abnormal retinal vascular development and angiogenesis." (PMID 32926103, 2020). "Pathogenic mutations in NDP and FZD4 lead to a number of retina-related diseases including FEVR, Norrie disease, persistent hyperplastic primary vitreous, advanced stage of retinopathy of prematurity, and Coats disease." (PMID 31827910, 2019). "Mutations in the NDP gene and the receptor genes, FZ4, LRP5, and TSPAN-12, have been identified for vitreoretinal diseases including Norrie Disease, Familial Exudative Vitreoretinopathy, and Coats' Disease." (PMID 26158506, 2015). "Norrie disease is caused by a X-linked recessive mutation of Norrie disease pseudoglioma gene (NDP), coding for Norrin/Norrie disease protein (Ndp)." (PMID 20150991, 2010). "However, there are reports showing overlapping features of Norrie disease and retinoschisis in a NDP knock-out mouse model and also the involvement of both the genes in retinoschisis patients." (PMID 34039417, 2021). "NDP is a particularly interesting target in the context of the proposal that FAD might have developmental consequences, in that 30% of patients with Norrie Disease, a disorder caused by mutation of NDP, have CNS deficits." (PMID 24416243, 2014). "There is increasing awareness that the clinical phenotype known as Norrie disease may not be exclusive to mutations in the NDP gene and there is a strong case for recessively inherited FZD4 mutations as a candidate gene in unsolved cases." (PMID 35651932, 2022). "We found that when FEVR and Norrie disease had been reported in the same family (by the same author) this was due to a difference in the genotype; for example one individual with Norrie disease was hemizygous whereas his relative with FEVR was heterozygous for the same pathogenic NDP mutation." (PMID 35651932, 2022). "Many of the ocular findings in OPPG patients overlap with those of FEVR and ND, caused by loss-of-function mutations in other Wnt signaling components, such as Frizzled-4 (FZD4) and Norrie disease protein (NDP)." (PMID 27031698, 2016).
Norrie disease (continued). "The Norrie disease protein (NDP) gene (OMIM 300658) often result in a severe phenotype is located on chromosome Xp11.3 (ChrX: 4,36,92,969–4,37,17,694) (GRCh37) and is considered the pathogenic basis of ND." (PMID 38146894, 2023). "Finally, concerning the Hedgehog pathway, while direct evidence of interaction is similarly lacking, in Norrie disease, expression of the NDP gene is initiated in retinal progenitor cells in response to Hedgehog signaling, which induces Gli2 binding to the NDP promoter." (PMID 41357583, 2025).
Familial exudative vitreoretinopathy (18 papers, 2010 to 2025). Familial exudative vitreoretinopathy (FEVR) is a rare hereditary vitreoretinal disorder characterized by abnormal or incomplete vascularization of the peripheral retina leading to variable clinical manifestations ranging from no effects to minor anomalies, or even retinal detachment with blindness. "To date, nearly 20 mutations in the NDP gene have been identified in individuals with X-linked familial and sporadic exudative vitreoretinopathy, however, all of them were missense mutations." (PMID 33588793, 2021). "In the retina, FZD4 and the ligand NDP are critical mediators of signalling and are mutated in familial exudative vitreoretinopathy." (PMID 28675177, 2017). "ND is ascribed to mutations of the NDP gene, which can also cause X-linked familial exudative vitreoretinopathy (XL-FEVR)." (PMID 21179243, 2010). "The missense mutation of the NDP gene can trigger familial exudative vitreoretinopathy (FEVR)." (PMID 41357583, 2025). "Mutations in NDP and FZD4 have been closely related to a series of retinal diseases including familial exudative vitreoretinopathy (FEVR)." (PMID 32420371, 2020). "Mutations in human genes NDP, FZD4, LRP5 and TSPAN12 cause familial exudative vitreoretinopathy, a potentially blinding disease initially characterized by retinal hypovascularization." (PMID 28675177, 2017). "In humans, mutations in NDP, FZD4, LRP5 or TSPAN12 genes are linked to familial exudative vitreoretinopathy (FEVR), which is characterized by retinal vascular defects, vision impairment, or blindness." (PMID 28675177, 2017). "Norrie's disease and familial exudative vitreoretinopathy (FEVR) are retinal conditions, which present similarly to ROP engendered, engendered by a single genetic variant many of which overlap with ROP including NDP, FZD4 TSPAN12, and LRP5 from our analysis." (PMID 37492605, 2023).
retinopathy of prematurity (10 papers, 2015 to 2024). A bilateral retinopathy characterized by neovascularization, scarring, retinal detachment, and eventually blindness. "NDP variants associated with retinopathy of prematurity are predominantly found in the 5′ and 3′ untranslated regions." (PMID 35651932, 2022). "Rarely variations in the NDP gene are known to cause diverse forms of NDP-related retinopathies such as Coat’s disease, X-linked familial exudative retinopathy, retinopathy of prematurity and persistent hyperplastic primary vitreous." (PMID 34039417, 2021). "Pathogenic mutations in NDP and FZD4 could lead to a series of retina-related diseases such as FEVR, Norrie, and retinopathy of prematurity (MIM#133780), which could be distinguished according to their unique characteristics." (PMID 32420371, 2020). "Furthermore, isolated NDP-associated ocular malformations may also be diagnosed as X-linked FEVR (OMIM: #305390), Coat’s disease (OMIM #300216), retinopathy of prematurity (OMIM: #133780), as well as PHPV." (PMID 38994994, 2024). "To date, NDP gene variants are associated with various retinopathy‐related diseases, including X‐linked familial exudative vitreoretinopathy (XL‐FEVR; OMIM #305390), Coat's disease (OMIM #300216), and retinopathy of prematurity (ROP), have similar ocular features to ND." (PMID 38146894, 2023).
Coats disease (9 papers, 2015 to 2025). Coats disease (CD) is an idiopathic disorder characterized by retinal telangiectasia with deposition of intraretinal or subretinal exudates, potentially leading to retinal detachment and unilateral blindness. "Somatic mutations in the NDP gene have been implicated in Coats' disease." (PMID 26413362, 2015). "This review summarises all variants in NDP that have been associated with ocular pathology to date including ND, FEVR, Coats disease and ROP and examines the correlation between the amino acid change and the severity of the clinical phenotype." (PMID 35651932, 2022).
retinal diseases (5 papers, 2016 to 2023). "This is the first time a variant in NDP has been associated with a retinal disease in the dog and also the first X-linked RD to be reported in the dog." (PMID 33945575, 2021). "Retinal diseases that can result in blindness in people that are known to be X-linked include retinoschisis and NDP (norrin cystine knot growth factor)-related retinopathies." (PMID 33945575, 2021). "Pathogenic variants in genes that play key roles within this pathway, such as NDP, FZD4, TSPAN12, and LRP5, have been associated with the incidence of these retinal diseases." (PMID 37947657, 2023).